IL6 (interleukin 6)
Diseases named in the same sentence as IL6 in open-access papers (continued):
Sharing a sentence is not in itself a finding about the gene and the disease.
colitis (continued). "When one considers that IL-6 production by macrophages in the gut has been linked to intestinal homeostasis and barrier function, IBD, colon cancer and colitis, this apparent stimuli of IL-6 production in the presence of CMC may be problematic." (PMID 37242982, 2023). "Finally, PR1P prevented weight loss and tissue injury and reduced plasma levels of key inflammatory cytokines IL-1β and IL-6 in a TNBS-induced colitis model in the rat." (PMID 37187742, 2023). "On the other hand, the animal group treated with curcumin nanostructured microemulsion had a significant reduction in the tissue levels of TNF-α (170.5 ± 5.01 pg/mL), as well as IL-1β and IL-6, compared to the colitis treated with NS, and to the COL/MES group rats." (PMID 35976279, 2022). "In addition, others have shown that giving mice DSS to induce colonic inflammation during stressor exposure exacerbates colitis, marked by increases in IL-6, IFNγ, and TNFα and colonic histopathology." (PMID 35216112, 2022). "In addition, in the colitis model, elevated levels of pro-inflammatory cytokines (TNF-α, IL-1β and IL-6) were found to enhance the inflammatory cascade and cause intestinal tissue damage in UC patients." (PMID 36555167, 2022). "Also, DSS-induced colitis increased systemic inflammation, as demonstrated by increasing IL-6 in serum level and elevated levels of IL-6 and TNF-α levels in cortical tissue, which then results in cortical inflammation." (PMID 35011101, 2022). "Moreover, GLPN with lower Mw fraction exhibited anti-inflammatory activity through preventing colon length shortening and inhibiting the production of pro-inflammatory cytokines including TNF-α, IL-1β, and IL-6 in DSS-induced colitis mice." (PMID 36245525, 2022). "Furthermore, the expression of TNF-α and IL-6 in peritoneal macrophages from mice with colitis was down-regulated by a high concentration (10 nM) of PYY 3–36." (PMID 35443853, 2022). "Disturbance of intestinal immune regulation is an essential factor in the pathogenesis of IBD, in which proinflammatory cytokines TNF-α, IL-6, IL-1β and anti-inflammatory cytokine IL-10 are the key indicators reflecting the degree of inflammation in the model of colitis." (PMID 36615796, 2022). "Moreover, the inflammatory process associated with colitis increases the production of inflammatory cytokines, mainly TNF and IL-6." (PMID 35295931, 2022). "However, further studies on signaling pathways involved in chronic inflammation-induced CRC, such as MAPK, IL-6/STAT3, COX-2/PGE2, and IL-23/Th17, are necessary to investigate the protective effect of DRB in the pathogenesis of colitis-associated CRC." (PMID 36360101, 2022). "Activation of nuclear factor-κB (NF-κB) signaling was observed in the colonic epithelial cells in colitis patients, which could further stimulate the formation of proinflammatory cytokines or mediators such as IL-6, IL-17, TNF-α, and COX-2." (PMID 35269566, 2022). "Our results showed that the regulatory effect of PAMK on the Th17/Treg balance in colitis may depend on the inhibition of the IL-6/STAT3 pathway." (PMID 36341374, 2022). "Furthermore, sulfasalazine and hFm alleviated cGm-induced colitis: they suppressed myeloperoxidase activity, IL-1β and IL-6 expression and increased IL-10 expression." (PMID 35631220, 2022). "Pathogenic bacteria of colitis such as Shigella, Oscillospira and Xenorhabdus, which were negatively correlated with most SCFAs, were significantly positively correlated with MPO, TNF-α, IL-1β, IL-6, IL-17, and IgE (P ≤ 0.05)." (PMID 36451737, 2022). "Furthermore, significantly low pro-inflammatory cytokine levels (TNF-α and IL-6) in the Cur-HA-PLGA-NP-treated group indicated colitis alleviation, which is generally high in chronic inflammation." (PMID 36297553, 2022).
colitis (continued). "In a colitis animal model induced by dextran sulfate sodium (DSS) and 2,4,6-trinitrobenzene sulfonic acid, maresin-1 suppressed disease activity in colitis and improved weight loss by decreasing IL-1β, TNF-α, IL-6, and IFN-γ in the acute phase." (PMID 35163291, 2022). "To prove this hypothesis, we used IL-6 antibody to systematically block the effect of IL-6, and observed the effects on colitis and CAC in mice." (PMID 35664068, 2022). "Furthermore, the HEBD increased the antioxidant defenses in the colon and hippocampus and reduced the myeloperoxidase activity and IL-6 levels in the colon from colitis mice." (PMID 35295931, 2022). "Our results suggested that PAMK treatment regulated the Th17/Treg cell balance to attenuate DSS-induced colitis in mice, which may be dependent on the inhibition of the IL-6/STAT3 signaling pathway." (PMID 36341374, 2022). "IFN-γ, IL-1β, and IL-6 also play a crucial role in the development of colitis." (PMID 35992694, 2022). "In addition, we found that the effect of P2Y13 on colitis is related to the activation of the IL-6/STAT3 pathway." (PMID 35982893, 2022). "Previous studies demonstrated that Uro-A reduced colon inflammation and improved intestinal barrier integrity in DSS-induced mouse models of colitis by reducing the cytokines interleukin 1 beta (IL-1β), interleukin 6 (IL-6), and tumor necrosis factor alpha (TNFα)." (PMID 35645801, 2022). "Furthermore, they proved that nicotine significantly reduced the number and size of colonic tumors in mice with colitis-associated cancer induced by administering azoxymethane and DSS through the IL-6/Stat3/miR-21 signaling pathway." (PMID 35251010, 2022). "Therefore, our findings suggest that PD increases the level of IL-6 to enhance epithelial restoration in the DSS-induced colitis mouse model." (PMID 35933374, 2022). "IL-6 activates NF-κB to regulate dextran sulfate sodium-induced colitis in mice." (PMID 36321893, 2022). "Interestingly, chemical stimulation with glutamic acid of the PVN, which is a major source of brain CRH, alleviated TNBS-evoked colitis as assessed by a reduction in colonic damage scores and levels of IL-6 and IL-17." (PMID 34983592, 2022). "NF-kB-mediated secretion of IL-6 from immune cells in cancer originating from colon inflammation appears to activate NF-kB and STAT3-dependent signaling in epithelial cells of the gastric mucosa, such as upregulation of DNA methyltransferase activity and associated methylome changes." (PMID 35757000, 2022). "LCS-SeNPs alleviate DSS-induced colitis in mice, probably because of its combined favorable effects, which inhibits pro-inflammatory cytokines (IL-6 and TNF-α) and the production of oxidative index MDA, promotes the production of GSH-Px resulting in the restoration of intestinal permeability." (PMID 36555167, 2022). "A correlation of DMBT1-/- mice and colitis could be confirmed, in which elevated levels for IL-6 and TNF during inflammation could be seen." (PMID 34989914, 2022). "Taken together, PTENΔDC mice show increased mortality and plasma IL-6 levels during colitis without any impact on weight loss or histological changes compared to WTs." (PMID 35514976, 2022). "Interestingly, serum levels of Il-1β, Tnf, and Il-6 in DSS-induced colitis are further increased by transient hypoxia." (PMID 36232412, 2022). "IL-23 exacerbates inflammation and may drive the conversion of colitis to CAC by promoting the release of IL-6 and IL-17." (PMID 36339623, 2022). "It was shown in a trinitrobenzene sulfonic acid (TNBS) and dextran sodium sulfate (DSS)-induced colitis model that overexpression of elafin led to restoration of proteolytic balance; downregulation of IL-6, IL-8, IL-17A, and NFκΒ; and inhibition of TNF-α–induced increased permeability." (PMID 36552023, 2022). "In addition, our results show that MRS2211 treatment can significantly inhibit the expression of IL-6 in DSS-induced colitis." (PMID 35982893, 2022).
colitis (continued). "Rev-erbα, a transcription factor, was reported to directly inhibit IL-6 expression in colitis." (PMID 36419076, 2022). "Overall, it is believed that IL-6 meditates pathogenicity of bacteria on colitis and the reduction of IL-6 might contribute to the resistance to the IRC." (PMID 36389768, 2022). "The deficiency of the TNF-α receptor or IL-6 in mice causes less severe inflammation upon DSS exposure, suggesting that these molecules and related signaling pathways play a key role in the pathogenesis of colitis." (PMID 36058917, 2022). "Together, these data revealed that PAMK treatment alleviated DSS-induced colitis by regulating the Th17/Treg cell balance, which may be dependent on the inhibition of the IL-6/STAT3 signaling pathway." (PMID 36341374, 2022). "CSC exposure activated the host immune response toward Helicobacter and Paraprevotella, increased the number of mesenteric lymph node cells, and promoted the release of IFN-γ and IL-6, which induced the progress of spontaneous colitis or the deterioration of experimental colitis." (PMID 36275694, 2022). "Notably, IL-6 was the most responsive to B. longum-Endo in treating colitis, with its expression level changed by 4.6 times after treatment." (PMID 35847065, 2022). "Furthermore, microbiota dependent TLR-mediated activation and IL-6 production by DCs leading to T cell activation are necessary for colitis induction." (PMID 35514976, 2022). "Odoribacter could stimulate the production of IL‐6 and IL‐1β and the expansion of Th17 cells to confer resistance to colitis and colon cancer." (PMID 36348804, 2022). "Overall, higher production of IL-6 and IL-1β in MCJ-deficient mice could indicate a higher presence of protective T cells, and therefore, resistance to colitis." (PMID 35705557, 2022). "CR dose-dependently down-regulated Nlrp3, IL-1β, IL-6, Tnf-α and Ccl2 mRNA levels in colitis mice." (PMID 34393786, 2021). "Also in this study, it was shown that cytokines produced by Th1 (i.e., TNF-α, IFN-γ) and Th17 cells (i.e., IL-17) or promoting Th17 cell differentiation (IL-1β, IL-6) were significantly increased in T cell transfer colitis mice compared to control mice." (PMID 34248633, 2021). "Beta-sitosterol was found to markedly reduce weight loss, colonic length shortening, and microscopic changes in DSS-induced colitis and to reduce TNF-α, IL-6, and IL-1β levels in the intestinal tissues of experimental colitis mice in a concentration-dependent manner." (PMID 34149863, 2021). "Curcumin could significantly inhibit the activation of NLRP3 inflammasome in DSS-induced mice, reduce the expression of IL-1, IL-6, and other inflammatory cytokines, and alleviate the symptoms of colitis in DSS-induced mice." (PMID 34055024, 2021). "In support of the possibility that colitis-associated inflammatory factors contribute to neuroinflammation, we observed increased plasma concentrations of TNFα, MCP-1/CCL2, IL-6, and IFNγ in colitic mice, as well as increased transcription of Tnf, Il1b, and Il6 in their brains." (PMID 34511110, 2021). "While the colitis-associated increase in serum tumor necrosis factor α (TNFα) levels was not exacerbated among genotypes, serum interleukin 6 (IL-6) levels were significantly increased in Usp22fl/fl animals undergoing acute colitis." (PMID 33920268, 2021). "The WT mice that were reconstituted with Drd5−/− bone marrow were more prone to DSS-induced colitis with greater body weight loss, a higher DAI score, shorter colons, and more infiltrating inflammatory cells as well as higher levels of TNFα, IL-6, and CCL2 in serum." (PMID 34884737, 2021). "Recently, when milk exosomes were fed to DSS (dextran sulfate sodium salt)-induced colitis model mice, the expression of the proinflammatory cytokines IL-6 and TNFα decreased compared with the control group, thereby reducing inflammation and improving necrotizing enteritis." (PMID 34831071, 2021).
colitis (continued). "Furthermore, the expression of proinflammatory cytokines, including TNFα and IL-6, significantly increased in mice with colitis, whereas the DSS + SP@Curcumin–treated group showed the similar expression to that of nontreated mice." (PMID 34818040, 2021). "TNF-α, IL-6, and IL-1β are the most important cytokines involved in the pathogenesis of colitis." (PMID 33854556, 2021). "However, oral gavage and intraperitoneal injection of buspirone alleviated IS-induced colitis: it suppressed myeloperoxidase activity, IL-1β, IL-6, and TNF-α expression, and NF-κB+/CD11c+ cell population in the colon." (PMID 33731795, 2021). "Besides its role in the stabilization of lipid rafts, apical protein trafficking and cell adhesion, galectin-4 was shown to exacerbate intestinal inflammation by stimulating CD4+ T-cells to produce IL-6 in a murine colitis model." (PMID 33805597, 2021). "Serum IL-6 was also elevated in acetic acid-induced colitis rats in our study." (PMID 33441125, 2021). "To assess whether the inhibitory effect of ZS40 on colitis was mediated by the NF-κB pathway, we measured the relative expression of IκB-α, NF-κBp65, IL-6, and TNF-α mRNA and protein in colon tissues." (PMID 34867317, 2021). "For example, caffeic acid, tea polyphenols, salvianolic acid, and sesamol could ameliorate colitis by reducing the levels of IL-1β, IL-6, TNF-α, and other pro-inflammatory cytokines in DSS-induced models." (PMID 35059326, 2021). "For example, caffeic acid, tea polyphenols, salvianolic acid, and sesamol could ameliorate colitis by reducing the levels of IL-1β, IL-6, TNF-α, and other pro-inflammatory cytokines in DSS-induced colitis mice." (PMID 34867926, 2021). "Tnf-α, Il-1β, Il-6, and iNOS are crucial in the pathogenesis of colitis." (PMID 33777833, 2021). "To evaluate colitis severity, we measured the expression of different pro-inflammatory cytokines and chemokines and found that the same supplement suppressed the pro-inflammatory cytokines IL-6 and TNFα and the chemokines Cxcl1 and Ccl3." (PMID 34071180, 2021). "In DSS-induced colitis mice treated with miR-19a mimic, colon tumor numbers, sizes and tumor loads are higher compared to the control group; pro-inflammatory cytokines, including IL-1β, IL-6, IL-17a, IFN-γ and TNF-α are also upregulated." (PMID 33921348, 2021). "In the CD45RBhi T cell transfer model of colitis, treatment with FAHF-2 decreased colitis progression as evidenced by decreased weight loss, histological inflammation and production of TNF-α, IFN-γ, IL-6, and IL-17 from the colon." (PMID 34926527, 2021). "In the TNBS-induced colitis mouse model, OCA was able to relieve colitis by reducing body weight loss, histological score, and expression of various inflammatory mediators (i.e., i-Nos, Ifn-γ, Il- 1β, Il-6, and Tnf-α) in a dose-dependent manner." (PMID 34064187, 2021). "Furthermore, a study reported that IL-6 monoclonal antibody treatment using DSS-induced colitis mouse models effectively suppressed the expression of claudin 2 and attenuated gut permeability." (PMID 34395495, 2021). "Thus, NAM had anti-inflammatory activity in mice with DSS-induced colitis by inhibiting the proinflammatory cytokines IL-6, IL-12p70, IL-1β, and TNF-α." (PMID 33748287, 2021). "It has been reported earlier that inhibiting the IL-6 signal pathway could reduce the many pro-inflammatory factors and improve the colitis." (PMID 33802553, 2021). "IAP ameliorated colitis in mice and inhibited LPS-induced IL-6 and TNF-α production." (PMID 34944428, 2021). "Inflammation in the colon (colitis) was confirmed in the same animals not only histologically but also biochemically, including analysis of colon level of pro-inflammatory cytokines (i.e., Il-1; Il-6 or TNF alfa) and CRP protein." (PMID 33499397, 2021).
colitis (continued). "Furthermore, while experimental colitis upregulated inflammatory genes in the colon, including Tnfa, Il6 and Ifng, UC patients also upregulated IL17A and IL10, followed by a slight increase in IL4 and mevalonate kinase (MVK) expression." (PMID 34434187, 2021). "Our results showed that GO treatment in the absence of colitis did not cause obvious changes in IL-6, IL-17, and IFN-γ expression." (PMID 33766052, 2021). "LTA reduced the lipopolysaccharide (LPS)-mediated histological damage, decreased the level of TNF-α, IFN-γ, IL-6 and IL-1β and enhanced the intestinal permeability by increasing the expression of certain tight junction proteins in LPS-induced murine model of colitis." (PMID 33219923, 2021). "In murine colitis model, colitis-induced wild type (WT) mice showed thrombocytosis and platelet aggregation, which were absent in IL-6-deficient mice." (PMID 34987523, 2021). "Some animal experiments by Wang and his workmates showed that ginsenoside Rg3 could significantly ameliorate DSS-induced colitis by inhibiting the expression of pro-inflammatory cytokines (IL-1β and IL-6)." (PMID 33462754, 2021). "In addition, probiotic treatment or FMT can reduce the expression and secretion of inflammatory factors (such as IFN-γ, IL-12, TNF-α, IL-6, and IL-1β) to resist colitis by regulating STAT1, STAT4, or NF-κB signals." (PMID 33532501, 2021). "Importantly, the concentrations of CCL-2, IL-1β, and IL-6 were significantly downregulated after DSS-induced colitis mice were treated with curcumin; IL-33 and IL-10 were significantly upregulated." (PMID 34567209, 2021). "As expected, the mRNA levels of Tnf and Il6 were markedly increased in colitis mice." (PMID 34630408, 2021). "In DSS-induced colitis in mice, digestion of preserved egg white ameliorated clinical symptoms, such as weight loss, disease activity index and inhibited secretion of pro-inflammatory cytokines TNF-α and IL-6." (PMID 33806061, 2021). "However, CSS treatment alleviated the RS-induced colitis: it inhibited colon shortening, suppressed myeloperoxidase activity and NF-κB activation (p-p65 to p65 ratio), and decreased IL-6 expression." (PMID 34391441, 2021). "This agrees with a previous study, according to which medium-chain glycerides could significantly reduce the level of proinflammatory cytokines, such as IL-6, IL-1, and relieve the inflammation of colitis in rats." (PMID 33053685, 2020). "Furthermore, dietary flavonoid isoliquiritigenin inhibits colitis-triggered tumorigenesis through blocking M2 macrophage polarization mediated by the interplay of prostaglandin E2 and IL-6." (PMID 32640667, 2020). "Furthermore, mRNA expression of genes encoding cytokines including IL-6, IL-1β, and TNF-α, and protein expression of COX-2 and iNOS were upregulated in the colon tissue of mice with DSS-induced colitis." (PMID 32059355, 2020). "The novel Five strains formulation was as effective as Vivomixx® in reducing the development of signs and symptoms of colitis and reduced the expression of pro-inflammatory mediators including Il-6 and Tnf-α while increased the expression of Il-10 mRNA and the number of Treg." (PMID 32629887, 2020). "Indeed, rosmarinic acid reduced the production of IL-6 in LPS-induced acute lung injuries and dextran sulphate-induced colitis in mice." (PMID 32426811, 2020). "Triptolide also suppressed IL-1β and IL-6 expression in mouse colitis tissue." (PMID 33240279, 2020). "The prevention of intestinal mucosal barrier injury observed in pioglitazone-treated mice with colitis was also associated with increased expressions of tight junction proteins and reduced protein levels of TNF-α, IL-6, and MMP9, which are soluble mediators controlled by the ERK-NF-κB." (PMID 31989391, 2020). "However, the treatment of colitis mice with ED amino acids effectively eliminated the DSS-mediated increase in IL-6 and reduction in IL-10 protein levels in the serum." (PMID 32855978, 2020).